MPO (myeloperoxidase)
Diseases named in the same sentence as MPO in open-access papers (continued):
Sharing a sentence is not in itself a finding about the gene and the disease.
asthma (continued). "Compared with patients with positive MPO-ANCA and negative ANCA, patients with PR3+ ANCA less frequently developed active asthma and peripheral neuropathy and more frequently had cutaneous manifestations and pulmonary nodules and lower eosinophil count." (PMID 35833130, 2022). "The median concentration in LC patients compared to healthy non-smokers, asthma sufferers, and smokers was more than 200% higher in SAA (771%), MMP-9 (743%), IL-8 (535%), CXCL9/MIG (482%), TNFRI (406%), Gro (331%), MPO (300%), Rantes (274%), Resistin (271%), TNFRII, and MIF (219%)." (PMID 32085733, 2020). "Although eosinophil-rich granulomatous inflammation and MPO-ANCA positivity may suggest eosinophilic granulomatosis with polyangiitis, predominant orbital and ENT involvement in the absence of asthma or other atopic features may be more consistent with localized granulomatosis with polyangiitis." (PMID 42018267, 2026).
Obesity (83 papers, 2012 to 2026). Accumulation of substantial excess body fat. "In this context, we observed an attenuated weight gain in both, a dietary and a genetic murine obesity model upon MPO deficiency." (PMID 40252642, 2025). "In the lung tissue, NOD1 deficiency during obesity led to elevated neutrophil accumulation, increased myeloperoxidase activity, reduced CD163+ macrophages, and enhanced β‐galactosidase activity." (PMID 40616268, 2025). "Elevated myeloid cell recruitment in PVAT is a hallmark of inflammation in obesity, which was reduced in MPO-deficient mice." (PMID 40252642, 2025). "Pulse wave velocity (PWV), a surrogate of arterial stiffness, was increased to about 1.5 m/s in both obesity models, whereas MPO deficiency alleviated PWV." (PMID 40252642, 2025). "Plasma MPO levels are inversely linked to obesity measures like weight, waist circumference, BMI, and insulin resistance." (PMID 38999869, 2024). "Summarizing the latest research on the inflammation of colorectal mucosa, it appears that obesity is most likely linked to the prevalence of MPO-positive cells within the colorectal mucosa, suggesting an underlying inflammatory response." (PMID 37629689, 2023). "High MPO levels are associated with an increment of oxidative stress and inflammation which are characteristic of overweight and obesity." (PMID 37107208, 2023). "For example, Cp binds the myeloperoxidase enzyme inhibiting its pro-oxidant functions in inflamed tissues (i.e., adipose tissue and liver) that have been associated with obesity and nonalcoholic steatohepatitis." (PMID 36674661, 2023). "The role of inflammation in the colorectal mucosa, as indicated by the presence of MPO-positive cells, and its association with obesity and adenoma occurrence is another critical aspect to consider." (PMID 37629689, 2023). "Parallel with these results, several studies reported that MPO was considered an early biomarker of inflammation and an obesity risk factor in obese individuals." (PMID 36248416, 2022). "Obesity was associated with significantly increased activity of MPO, a marker of neutrophil infiltration into the gastric mucosa." (PMID 33637683, 2021). "This study aims to evaluate the plasma MPO and ANGPTL6 levels in obese and diabetic individuals as well as MPO association with biochemical markers of obesity." (PMID 32277104, 2020). "In concordance, we observed that MPO inhibition through AZM198 treatment was associated with positive effects on obesity and adipose tissue inflammation." (PMID 31822739, 2019). "The major role of MPO is in host defense, but it is also associated with obesity, insulin resistance, hypertension and heart failure." (PMID 31822739, 2019). "Moreover, concentrations of the MPO–DNA complexes before bariatric surgery were associated with cardiometabolic risk factors, such as proxy measures of obesity, blood pressure (BP), and markers of glucose metabolism, but not with lipids profile." (PMID 39861371, 2025). "The activity of MPO or another stress source caused by obesity may lead to an increase in this oxidation." (PMID 40900465, 2025). "MPO has also been shown to be causally linked to development of obesity and insulin resistance." (PMID 38685051, 2024). "In addition, MPO-deficient mice are resistant to diet-induced obesity and IR; inhibition of MPO activity in neutrophils decreases diet-induced IR in obese mice, and activation of MPO is associated with the development of obesity and obesity-associated IR." (PMID 36595188, 2023). "Thus, plasma MPO levels, which are indicators of circulating neutrophils activity, are raised in patients with severe obesity, cardiovascular risk and poor prognosis." (PMID 35818731, 2022). "Thus, further longitudinal studies about the causal relationship between ANGPTL6 and MPO in T2D and obesity must be conducted." (PMID 32277104, 2020).
Obesity (continued). "Considering that several studies suggest a modified effect of known genetic and environmental factors such as MPO gene polymorphism, family history, obesity, or alcohol use by menopausal status, a detailed approach stratified by menopausal status with larger sample size is warranted." (PMID 32300124, 2020). "Myeloperoxidase (MPO) is positively associated with obesity and diet-induced insulin resistance." (PMID 32277104, 2020). "Mice deficient in MPO are resistant to diet-induced obesity and insulin resistance, indicating that MPO may have a regulatory role in obesity." (PMID 32277104, 2020). "Furthermore, augmented MPO levels have been associated with obesity, chronic low-grade inflammation, insulin resistance, MetS, and type 2 DM." (PMID 31443320, 2019). "The activation of MPO may contribute to the development of obesity and obesity-associated insulin resistance." (PMID 28105924, 2016). "This disparity between obese and lean patients to develop obesity-associated diseases upon inhalation of air pollutants can be prevented by blocking free radical processes in the obese lung with specific antioxidants that target MPO or MPO-derived oxidants, such as HOCl." (PMID 39450269, 2019). "Interestingly, relationships between overweight/obesity and radiotoxicity risk seem to be more evident in women with endothelial nitric oxide synthase (eNOS) and myeloperoxidase (MPO) genotypes associated with higher levels of nitric oxide and reactive oxygen species (ROS)." (PMID 30634494, 2019). "Targeting the lung by using MPO inhibitors or HOCl scavengers may prove to be effective to prevent the contribution of pulmonary neutrophilic inflammation towards systemic inflammation, the leading cause of obesity-associated metabolic abnormalities." (PMID 39450269, 2019). "We found that baseline MPO levels were significantly higher in obese individuals when compared with LC irrespective of presence of MetS, which suggests that MPO may reflect an increased oxidative stress linked to obesity." (PMID 24455214, 2013). "Furthermore, our data indicate a general role for MPO in the chronic inflammation associated with obesity and insulin resistance, and therefore argue for a re-evaluation of the role of neutrophils and their cytotoxic products in the pathogenesis of metabolic disease." (PMID 23285030, 2012). "Here, we demonstrate a strong interdependency between PVAT inflammation and MPO-mediated phenotypic changes impeding PVAT beiging in obesity." (PMID 40252642, 2025). "Patients living with severe obesity (mean BMI: 45.5 kg/m2) displayed significantly higher plasma concentrations of NETs (MPO–DNA complexes) than lean, healthy controls." (PMID 39861371, 2025). "Herein, we demonstrate that the neutrophil-derived heme-peroxidase MPO impacts on vascular function in obesity by changing paracrine and phenotypic properties of PVAT." (PMID 40252642, 2025). "Obesity increased MPO plasma and PVAT levels and was accompanied by enhanced myeloid cell frequency, which was curbed by MPO deficiency." (PMID 40252642, 2025). "Individuals with obesity exhibit higher plasma and adipose tissue levels of MPO-DNA complexes than eutrophic controls." (PMID 41550876, 2025). "Improvement of endothelial function inversely correlated with circulating MPO levels, suggesting MPO as a biologically relevant mediator of adipose tissue metabolism and vascular function in obesity." (PMID 40252642, 2025). "In obesity, immune cells, including myeloperoxidase (MPO)-releasing myeloid cells, accumulate in PVAT." (PMID 40252642, 2025). "MPO contributes to PVAT dysfunction in obesity in an APN-dependent manner, leading to pro-contractile and deleterious adipokine signaling, ultimately impairing endothelial function." (PMID 40252642, 2025). "Serum myeloperoxidase (MPO) activity is correlated with obesity, insulin resistance, liver injury, and inflammation." (PMID 40584440, 2025).
Obesity (continued). "In individuals with obesity, neutrophils exhibit an activated phenotype, indicated by increased plasma concentrations of myeloperoxidase (MPO) and neutrophil elastase (NE) compared to healthy controls." (PMID 39769394, 2024). "A pro-inflammatory condition in human obesity is supported by the higher myeloperoxidase (MPO) activity from neutrophils isolated from obese subjects compared with lean subjects." (PMID 39770044, 2024). "Based on several observed correlations and its evident elevation in children with obesity, we consider MPO a promising biomarker with potential for inclusion in the clinical workup in children and adolescents with obesity." (PMID 39857642, 2024). "To conclude, the present study showed elevated levels of MMP-9 and MPO and reduced levels of MIF of PWS, which are altered beyond comorbid obesity and clinical cardiovascular risk factors." (PMID 37430349, 2023). "Overall, our results show that circulating V associates with oxLDL, Co with adiponectin and MPO, Zn with leptin, and Rb with MPO and oxLDL in individuals with obesity and metabolic disorders." (PMID 38075040, 2023). "The mean level of serum MPO in patients with obesity was 20% higher than that in post CR intervention (p < 0.001)." (PMID 34202775, 2021). "Macrophages M2 are the most abundant innate immune cells activated in obesity, but recent studies showed that neutrophil activation also mediates subclinical inflammation in obesity mainly via elastase and myeloperoxidase secretion." (PMID 33803348, 2021). "Chicoric acid was found to reduce lipid peroxidation and increase the antioxidants activity and TAC in liver of mice and prevent inflammations of hepatic cells associated with obesity via decreasing the IL-6, TNF-α, and MPO activity." (PMID 34827094, 2021). "Baseline data confirmed advanced age (more than 70% were >80 years old), obesity, low SaO2, and low functional capacity in the MPO-Ps, together with the inability of some of them to carry out the tests." (PMID 34501486, 2021). "It has been shown that the progression of metabolic disturbances accompanying obesity is paralleled by increase in myeloperoxidase activity, NO formation as well as protein nitrosative damage." (PMID 33158288, 2020). "Evidence for the role neutrophil activation in obesity includes the increased expression of the activation marker CD66b and increased circulatory neutrophil-released myeloperoxidase and calprotectin." (PMID 32215785, 2020). "Myeloperoxidase contributes to the development of obesity and its ablation or inhibition prevents weight gain and IR." (PMID 32215785, 2020). "Multivariate logistic regression analysis was performed to ascertain the association between MPO, ANGPTL6 and the outcome of T2D and obesity." (PMID 32277104, 2020). "In conclusion, we showed that MPO activity, NO formation, and nitrosative damage to proteins parallel the progression of metabolic disturbances of obesity." (PMID 32963689, 2020). "It has shown that the progression of metabolic disturbances, accompanying obesity, is paralleled by increased MPO activity, NO formation, and nitrosative protein damage." (PMID 32963689, 2020). "Altogether, MPO presents an attractive target for pharmacological interference in obesity and hypertension, with possible (in)direct cardiac protective effects." (PMID 31822739, 2019). "All of these observations indicate the probability that MPO targets white and brown fat and is a chief contributor to the progression of inflammation-induced obesity, but this assumption also requires further investigation." (PMID 29669993, 2018). "A proper mechanism to justify the regulation of MPO activity in cases of obesity requires further research." (PMID 29669993, 2018). "A study of MPO as an early biomarker of inflammation and obesity in prepubertal obese children indicated an MPO level of about 22 μg/L, as compared to normal weight children with an MPO level of about 14 μg/L." (PMID 29669993, 2018).
Obesity (continued). "The data presented here show a marked reduction in MPO and ENA-78 levels with weight loss, suggesting the overall positive effects of weight loss on the chronic inflammatory state that defines obesity." (PMID 29238916, 2018). "Several oxidative enzymes such as myeloperoxidase (MPO) and lipoxygenases have been shown to involve in LDL oxidation and are associated with the development of obesity along with inflammation and insulin resistance." (PMID 26435910, 2015). "Further research focusing on the roles of LDL, OXLDL, MPO, and CRP may provide deeper insights into the mechanisms underlying microvascular dysfunction in obesity." (PMID 40900465, 2025). "Likewise, MPO, typically elevated in obesity-related inflammatory and oxidative states, exhibited only a non-significant downward trend in our model." (PMID 40563378, 2025). "It is possible that these effects may also be due to MPO, CRP, or other inflammatory or oxidative mediators associated with obesity." (PMID 40900465, 2025). "In humans, MPO is upregulated in obesity, independently of T2DM status." (PMID 38685051, 2024). "MPO presence suggests increased oxidative stress in obesity." (PMID 38999869, 2024). "Children with obesity or overweight had lower vitamin D levels, increased blood pressure, visceral and subcutaneous fat thickness, and higher leukocytes, C-reactive protein, and myeloperoxidase levels." (PMID 39408928, 2024). "Previous studies have shown that kaempferol can alleviate disease symptoms by inhibiting neutrophil infiltration or the activity of MPO in the high-fat-diet-induced obesity model, the lung I/R injury model, the keratitis model and the gastric mucosal injury model." (PMID 36293548, 2022). "The main explanation of the role of NETs in obesity-induced endothelial dysfunction might be an abnormal production of MPO." (PMID 31963447, 2020). "In addition, the inhibition of MPO was found useful in preventing the production of pro-oxidants and insulin resistance; therefore, it can be a potential treatment for obesity and insulin resistance." (PMID 32277104, 2020). "Moreover, it has been also reported that MPO activity progressively increases with obesity and MetS." (PMID 32178436, 2020). "Myeloperoxidase and HOCl may be another target for preventing pulmonary neutrophilic inflammation in obesity." (PMID 39450269, 2019). "Indeed, neutrophils, MPO and markers of HOCl-promoted oxidations have been observed in the lung of obese patients and in mouse models of diet-induced obesity and metabolic syndrome." (PMID 39450269, 2019). "Attenuating myeloperoxidase (MPO) activity, an inflammatory enzyme associated with obesity, hypertension and heart failure, could have protective effects on multiple organs." (PMID 31822739, 2019). "In this study we investigated the effects of the novel myeloperoxidase (MPO) inhibitor AZM198 on obesity, liver damage and cardiac function in an obese and hypertensive mouse model, provoked by a high fat diet (HFD) combined with angiotensin II (AngII) infusion (HFD/AngII model)." (PMID 31822739, 2019). "In addition, it is reported that CXCL1 gene expression in the liver is elevated, and that the number of myeloperoxidase-positive neutrophils is increased, by provoking Fas-induced apoptosis in the livers of mice with obesity induced by a high-fat diet." (PMID 23875831, 2013). "In patients with obesity, the amounts of plasma ecDNA or MPO-DNA complexes correlate directly with measures of adiposity, markers of inflammation, glucose, and lipid metabolism, suggesting that NETosis may represent a link between overfeeding and obesity-associated dysmetabolism." (PMID 41550876, 2025). "Thus, reducing MPO activity may help prevent or treat obesity, insulin resistance, and inflammation." (PMID 40584440, 2025). "Interestingly, boys with overweight or obesity had higher levels of MPO." (PMID 39857642, 2024).